DANCR (differentiation antagonizing non-protein coding RNA)
Diseases named in the same sentence as DANCR in open-access papers (continued):
Sharing a sentence is not in itself a finding about the gene and the disease.
tumor (continued). "In addition, the increased DANCR expression in the serum originates from tumor expansion (tumor cells derived) or excessive inflammatory response (monocytes derived) is another important question to be addressed." (PMID 29416741, 2018). "Moreover, DANCR knockdown inhibited tumor metastasis in vivo." (PMID 41602364, 2026). "has indicated that plasma levels of DANCR and SNHG1 in HCC patients correlate significantly with those in cancer tissues, showing strong associations with critical clinical parameters such as microvascular invasion, invasion of the liver capsule, tumor dimensions, TNM staging, and AFP levels." (PMID 41474641, 2026). "Thus, our finding revealed a new mechanism by which DANCR regulates LIPG expression in tumor cells." (PMID 35954428, 2022). "Similarly, knockdown of DANCR inhibited tumor growth and KLF8 expression in vivo, suggesting that DANCR may play an essential role via miR-135a-5p/KLF8 axis." (PMID 34722539, 2021). "In addition, DANCR knockdown inhibited NPC tumor growth in vivo." (PMID 34722539, 2021). "Interestingly, DANCR has also been suggested as a tumor suppressor in BC." (PMID 34722539, 2021). "Likewise, silencing of DANCR in CC cells inhibited tumor formation and metastasis in vivo." (PMID 32423468, 2020). "Furthermore, proliferation marker Ki67 staining displayed that the subcutaneous tumor formed by DANCR depleted C-33A cells had much less Ki67 positive cells than that formed by control C-33A cells, which further supports the anti-proliferative roles of knockdown of DANCR in vivo." (PMID 32123519, 2020). "It showed that the tumor size and weight could be suppressed by knockdown of DANCR." (PMID 31827393, 2019). "Additionally, our study suggested that DANCR may regulate mammalian target of rapamycin (mTOR) expression through sponging miR‐496, thus modulating tumour growth." (PMID 29266795, 2018). "DANCR knockdown suppresses PTEN, a well-established tumour suppressor, thereby augmenting the radiosensitivity of NPC cells." (PMID 38877534, 2024). "For example, DANCR regulates endothelial lipase (EL/LIPG), a pivotal modulator of tumour cell metabolism, by binding to LIPG and modulating the stable expression of the LIPG protein in TNBC cells." (PMID 38877534, 2024). "Their work indicated that cynaroside, a novel LIPG inhibitor, effectively suppresses DANCR expression in TNBC cells, significantly impeding tumour formation." (PMID 38877534, 2024). "Functioning as a tumour promoter in CRC cells, DANCR expression is significantly increased in CRC tissues compared to adjacent nontumour tissues." (PMID 38877534, 2024). "Lnc-DANCR knockdown prevents EZH2 from binding to the SOCS3 promoter, leading to SOCS3 upregulation, which in turn inhibits tumor growth." (PMID 39830662, 2024). "Mechanistically, ZNF750 has been reported to mediate tumor-suppressive roles by regulating the expression of various downstream genes, such as TINCR, LAMC2, DANCR, FGF14, and SNAI1." (PMID 37365152, 2023). "Thus, we hypothesized that DANCR may impact LIPG protein expression in tumor cells." (PMID 35954428, 2022). "To analyze the interaction between DANCR and LIPG inside tumor cells, we developed an MCP-MS2 system in which GFP-tagged MCP bound to MS2 stem loop sequences that can be immunoprecipitated using antibodies to identify DANCR binding." (PMID 35954428, 2022). "A large number of studies have reported that targeted inhibition of DANCR, SLCO4A1-AS1, Linc00337, SNHG7/20, NEAT1, MALAT1, ES1 or MALAT1 can reduce the degree of malignancy of tumours at the cellular level and even in animal models." (PMID 35907897, 2022). "Further, we revealed that the DANCR-LIPG axis can mediate OXPHOS and oleic acid uptake in tumor cells." (PMID 35954428, 2022). "Based on their results, DANCR is up‐regulated following hepatitis C virus infection and recognized as the lncRNA most relevant to hepatitis C virus‐related HCC in tumour tissues." (PMID 34907642, 2022).
tumor (continued). "In the current experiments, we set about to examine the regulatory effects that IGF2BP2 on GBM cell chemoresistance and analyze the potential regulatory network of the IGF2BP2/DANCR/FOXO1/PID1, aiming to provide a novel antitumor target for tumor treatment." (PMID 35141227, 2021). "Tumor-suppressive miR-34c was often downregulated in various types of tumor cells and regulated EMT through direct binding with SOX9, SATB2, MAP3K2, and DANCR mRNA." (PMID 32252322, 2020). "Furthermore, proliferation marker Ki67 staining displayed that the subcutaneous tumor formed by DANCR overexpressed HeLa cells had much more Ki67 positive cells than that formed by control HeLa cells, which further supports the pro-proliferative roles of upregulation of DANCR in vivo." (PMID 32123519, 2020). "DANCR was upregulated by SALL4 and exerted its tumor-promoting roles partly through the activation of β-catenin pathway." (PMID 33123287, 2020). "Before the experiments, we compared the expression of DANCR between PTC and non-tumor thyroid tissues in three GEO datasets (GSE33630, GSE50901, and GSE66783)." (PMID 30910839, 2019). "In vivo, the tumor growth and the expression of matrix metalloproteinase (MMP)-2/9 and KLF8 were also blocked by DANCR inhibition." (PMID 31827393, 2019). "DANCR is upregulated by SALL4 and exerts its tumor-promoting roles partly through the activation of β-catenin pathway." (PMID 29416741, 2018). "In this study, we demonstrated a new mechanism by which DANCR-upregulated PI3K/AKT signaling pathway through activating serine phosphorylation of RXRA protein is important for TNBC cell proliferation and tumor growth." (PMID 30518934, 2018). "Knockdown of DANCR significantly inhibited TNBC cell proliferation, colony formation in vitro, and tumor growth in vivo." (PMID 30518934, 2018). "MALAT1, NEAT1, HEIH, HULC, HOTTIP, HOTAIR, and DANCR/ANCR function as oncogenic lncRNAs in HCC, promoting cancer progression through mechanisms such as activating oncogenic splicing factors, sponging tumor suppressor miRNAs, and altering gene expression patterns." (PMID 40700094, 2025). "In contrast, DANCR knockdown in colon cancer cells can directly interact with and increase the expression of miR-125b-5p, which targets hexokinase 2 (HK2), thus suppressing glycolysis and enhancing DDP sensitivity in tumour cells." (PMID 38877534, 2024). "Increased DANCR levels enhance the growth and liver metastasis of CRC tumours." (PMID 38877534, 2024). "Furthermore, DANCR influences lymphangiogenesis by regulating VEGF-C expression, impacting tumour angiogenesis and progression." (PMID 38877534, 2024). "DANCR binds to LIPG, enabling tumor cells to maintain LIPG protein stability and OXPHOS." (PMID 35954428, 2022). "DANCR binds to LIPG, which enables tumor cells to maintain the expression." (PMID 35954428, 2022). "In conclusion, this study elucidates a mechanism by which IGF2BP2 promotes DANCR expression and stability through FOXO1 ubiquitination-mediated PID1 expression, thereby promoting cancer cell survival and tumor growth as well as promoting the resistance of GBM cells to etoposide." (PMID 35141227, 2021). "Together, our study uncovered the oncogenic role of KLF5-dependent lncRNA DANCR transcription in GC in vivo and in vitro, which implicates the miR-194/AKT2 axis in tumor growth regulation, and it may be a potential therapeutic target for human GC." (PMID 34548487, 2021). "Unexpectedly, we failed to observe the relationship of lncRNA DANCR expression with tumor size or differentiation; however, it should be noted that the results were not reliable enough because of the distinct heterogeneity amongst included studies." (PMID 30910838, 2021). "We further verified the remarkable increased expression levels of DANCR in a cohort of 17 paired CCA tumor tissues and adjacent nontumor tissues, which was consistent with the results from high-throughput data." (PMID 31383847, 2019).
tumor (continued). "Although miR-135a-5p had been identified to target DANCR and be beneficial for TSCC progress, whether miR-135a-5p was responsible for the effects of DANCR on tumor malignancies was unclear." (PMID 31827393, 2019). "Overall, these in vivo results show that DANCR may activate the expression of KLF8 and MMPs to affect TSCC tumor growth." (PMID 31827393, 2019). "The expression levels of DANCR were significantly correlated with tumor size, lymphatic metastasis, invasion depth and TNM stage, suggesting that serum DANCR may be used as an easier and convenient diagnosis biomarker for GC." (PMID 29416741, 2018). "Our results showed that the expression of DANCR was higher in the tumor tissues than that in the adjacent non-cancerous tissues." (PMID 29416741, 2018). "Furthermore, DANCR contributes to protein assembly and modification, and the activation of the Wnt/β-catenin signaling pathway and the PI3K/AKT pathway, subsequently leading to rapid tumor growth and chemotherapy failure." (PMID 35954428, 2022). "Although the mechanism was not revealed, these findings suggested that DANCR might act as a tumour inhibitor in RCC." (PMID 33968736, 2021). "Following statistical analysis showed no conspicuous variation in serum DANCR expression in terms of age, gender, grade of tumor differentiation and tumor size in the CRC patients (P>0.05), while conspicuous variations were observed among different TNM stages (P<0.05)." (PMID 32159208, 2020). "In addition, the expression of DANCR and LIMK1 was investigated in xenograft tumours by qRT‐PCR." (PMID 31038266, 2019). "Furthermore, we found that knockdown of DANCR increased the expression of TIMP2/3 in the metastatic foci of CW22Rv1-shDANCR compared with those of CW22Rv1-shNC, as detected by immunohistochemistry analysis of mouse metastatic tumor tissues." (PMID 27191265, 2016). "Notably, DANCR expression did not increase significantly when the tumour diameter was ≤ 1 cm." (PMID 38877534, 2024). "Given that the DANCR/miR-4707-3p/FOXC2 axis in ESCC, we hypothesize ZNF750 may directly downregulate DANCR expression, strengthened the interaction of miR-4707-3p with FOXC2-3′UTR in a ceRNA manner, leading to degradation of FOXC2 mRNA, thus playing tumor suppressive role in ESCC." (PMID 32341351, 2020). "Although MLL3 acts as a tumour suppressor protein, DANCR does not influence MLL3 regulation in early PAAD stages; however, DANCR downregulates MLL3 in advanced stages, promoting cancer progression." (PMID 38877534, 2024).
cancer (81 papers, 2014 to 2026). A tumor composed of atypical neoplastic, often pleomorphic cells that invade other tissues. "Although several expression assays have assessed expression levels of DANCR in biological samples obtained from different types of cancers, the underlying cause of dysregulation of DANCR in cancer has not been identified." (PMID 35590326, 2022). "Over-expression of DANCR has also been associated with resistance to anti-cancer agents such as cytarabine, sorafenib, cisplatin and docetaxel." (PMID 35590326, 2022). "In this review, we summarized the current evidence regarding the function and underlying mechanism of DANCR in numerous cancers." (PMID 34722539, 2021). "Among the lncRNAs, DANCR, encoded by a gene located in human chromosome 4q12, plays an important role in different cancers." (PMID 35096852, 2021). "Lnc-DANCR is reported to be associated with the development, progression, and metastasis of various human cancers." (PMID 32505219, 2020). "Recent studies indicated that DANCR was up-regulated in a large variety of cancers and thereby of high diagnostic value for great clinical value for cancer therapy." (PMID 29301870, 2018). "DANCR has also been implicated in various inflammatory diseases beyond cancer." (PMID 41394397, 2025). "Cancer-associated lncRNAs expressed from equivalent regions in vertebrate genomes, exemplified by DANCR, may therefore act as conserved regulators of both embryonic development and tumorigenesis." (PMID 41336739, 2025). "For instance, lncRNA DANCR (also known as ANCR) is a cancer-associated lncRNA, and dysregulation of DANCR affects cancer cell proliferation, apoptosis, migration, and invasion through different mechanisms, including acting as a miRNA sponge, stabilizing mRNA, and interacting with proteins." (PMID 39595204, 2024). "Thus DANCR can be used as a promising diagnostic and prognostic biomarker and therapeutic target for various types of cancer." (PMID 34722539, 2021). "Many researches have tried to elucidate the prognostic role of lncRNA DANCR expression in cancers; however, the underlying mechanism remains unclear." (PMID 30910838, 2021). "Future efforts focused on investigating the functional role of DANCR in chemoresistance could help to broaden our knowledge on cancer‐associated activities of DANCR." (PMID 33638615, 2021). "As our analysis of TCGA data and previous reports suggested, increased DANCR expression is associated with poorer prognosis, and may potentially be related to more aggressive cancer types." (PMID 33302540, 2020). "Subsequent studies demonstrated that DANCR is a promising cancer-associated lncRNA." (PMID 32123519, 2020). "In addition, DANCR has been implicated in regulating cancer cell proliferation, apoptosis, migration and invasion and be associated with poor prognosis." (PMID 33123287, 2020). "Despite the recognised importance of DANCR in cancer, its function in normal development and physiology is less well understood." (PMID 41336739, 2025). "By acting as a competitive endogenous RNA for miRNAs and by interacting with proteins and mRNAs at the molecular level, DANCR contributes significantly to cancer progression." (PMID 38877534, 2024). "DANCR plays a crucial role in the development of multiple types of human cancers, while the invasion phenotype and growth of lung tumors were repressed by shRNA treatment." (PMID 39119602, 2024). "These discrepancies suggest that the distinct expression profiles and functional roles of DANCR across various cancer types and cell lines significantly influence disease progression and clinical outcomes." (PMID 38877534, 2024). "In summary, the regulatory mechanisms of DANCR in cancer are multifaceted and hold significant promise for cancer research and treatment." (PMID 38877534, 2024). "For instance, DANCR has been found to contribute to the taxol resistance of in this type of cancer via modulation of miR-33b-5p/LDHA axis." (PMID 37025585, 2023).
cancer (continued). "Previous study also demonstrated the angiogenic role of DANCR in promoting several cancers progression 25,26." (PMID 37215458, 2023). "As part of this exercise, we confirmed MALAT1 and DANCR expression across a range of cancers and normal tissue." (PMID 36841868, 2023). "At present, previous studies have shown that DANCR expression is significantly increased in a variety of tumors and has cancer-promoting effects." (PMID 37060505, 2023). "Accumulation studies revealed that dysregulated glucose metabolism influenced chemosensitivity of cancer cells; we evaluated the roles of DANCR in glucose metabolism of PCa cells." (PMID 35571619, 2022). "Consistent with previous reports in various cancers, DANCR was also highly expressed in both PC cells and tissues." (PMID 35936737, 2022). "Due to its pan-oncogenic effect, DANCR has been considered to be a candidate cancer therapeutic target." (PMID 36497269, 2022). "Mechanistically, DANCR facilitates progression of this cancer through sponging miR-125b-5p and activating MAPK pathway." (PMID 35590326, 2022). "Since several signaling pathways are influenced by DANCR, drugs targeting this lncRNA are expected to affect numerous aspects of carcinogenesis, thus being effective in treatment of a wide range of cancers with different biological behaviors." (PMID 35590326, 2022). "IGF2BP2 and lncRNA DANCR have been reported to interact and promote the cancer stemness-like properties of pancreatic cancer." (PMID 35004679, 2021). "In our study, we discovered that high lncRNA DANCR expression was significantly associated with shorter OS and DFS in cancers." (PMID 30910838, 2021). "Subsequently, in recent decades, many studies have been carried out to understand the function of DANCR in cancer." (PMID 34722539, 2021). "In conclusion, the upstream and downstream mechanisms of DANCR are multifaceted and play vital roles in human cancers." (PMID 34722539, 2021). "This review focuses on the role and mechanism of DANCR in cancer progression with an emphasis on the clinical significance of DANCR in human cancers." (PMID 34722539, 2021). "DANCR has been reported to play an oncogenic role in various cancer cells by increasing stemness features and promoting tumor progression." (PMID 34065991, 2021). "Due to these oncogenic roles, as one of the critical regulatory RNAs in human cancers, DANCR was proposed to be a potential therapeutic target that holds a great promise for future cancer therapy." (PMID 33638615, 2021). "Recently, accumulating studies have supported a substantial role of lncRNA DANCR expression in the cancer prognosis." (PMID 30910838, 2021). "High lncRNA DANCR expression was associated with shorter OS, shorter DFS, and worse clinicopathological features compared with low lncRNA DANCR expression in human cancers." (PMID 30910838, 2021). "Recently, DANCR has been shown to be frequently dysregulated in different cancers and have plenty functions in a wide range of biological processes, including cell proliferation, cell apoptosis, cell autophagy, cell migration, invasion, and differentiation." (PMID 32099526, 2020). "In the present study, we specifically examined the functional roles of DANCR in regulating EMT, cancer stemness, and inflammation, and explored the molecular mechanisms mediating the actions of DANCR." (PMID 31860165, 2020). "Since DANCR has also been reported to promote cancer stemness-like properties, we focused on DANCR in this study." (PMID 31804607, 2020). "It has also been reported that IGF2BP2 regulates lncRNA DANCR through m6A modification, and IGF2BP2 and DANCR jointly promote the stemness-like characteristics of cancer and the pathogenesis of PC." (PMID 32754191, 2020).